SNORD115-31 (small nucleolar RNA, C/D box 115-31)
Synonyms: HBII-52-31
Gene: Small nucleolar RNA gene on chromosome 15 (25,227,109 to 25,227,190, forward strand). Ensembl gene ENSG00000202188.
Gene Ontology:
Biological process: RNA processing
Cellular component: nucleolus
Homologues: Orthologues: macaque SNORD115 (96% identical). Paralogues in human: SNORD115-26 (98% identical), SNORD115-11 (96% identical), SNORD115-29 (96% identical), SNORD115-36 (96% identical), SNORD115-41 (96% identical), SNORD115-43 (96% identical), SNORD115-12 (95% identical), SNORD115-16 (95% identical), SNORD115-22 (95% identical), SNORD115-39 (95% identical), SNORD115-44 (95% identical), SNORD115-6 (95% identical), and 37 more.